HIF1A (hypoxia inducible factor 1 subunit alpha)
Diseases named in the same sentence as HIF1A in open-access papers (continued):
Sharing a sentence is not in itself a finding about the gene and the disease.
lung carcinoma (continued). "FAM83A-AS1 was suggested to affect lung cancer cell invasion and migration through miR-150-5p/MMP14 signaling or miR-495-3p and may promote lung cancer progression through increasing FAM83A expression or glycolysis via regulating HIF-1α degradation." (PMID 35635086, 2022). "The integrity of HIF-1α/ATAD2 triggered by CIH may determine the aggressiveness of lung cancer through the interaction of mtROS and stemness in lung cancer cells." (PMID 36008934, 2022). "In lung cancer, miR-23a secreted in tumor-derived exosomes in hypoxia was reported to target the key HIF-1α regulators (propyl hydroxylases PHD1 and PHD2), thereby sustaining the overexpression of HIF-1α and promoting angiogenesis." (PMID 36176760, 2022). "PVT1 is highly expressed in lung cancer and cell lines, and the expression of PVT1 is regulated by HIF-1α, and the luciferase reporter assay and CHIP-qPCR analysis indicated that HIF-1α could bind to the promoter region of PVT1 and regulate PVT1 expression." (PMID 35256612, 2022). "HIF1α binds to the promoter of GDH and promotes GDH gene transcription in lung cancer cells." (PMID 36497259, 2022). "The present study also suggests a novel mechanism by which the integrity of CIH-triggered HIF-1α/ATAD2 may determine lung cancer aggressiveness via the interplay of mtROS and stemness in lung cancer cells." (PMID 35672694, 2022). "HIF-1α protein levels are notably downregulated by chlorogenic acid without changes in mRNA amounts in lung cancer cells exposed to cobalt (II) chloride (CoCl2), a hypoxia-mimetic agent." (PMID 34575983, 2021). "Similarly, a contribution of HIF-1α to the hypoxia-induced expression of LC3-II and autophagy was suggested as the radioprotective mechanism acting in the hypoxic cells of lung cancer and osteosarcomas." (PMID 33806538, 2021). "Interestingly, we found that lung cancer patients with positive TGF-β and HIF-1α expression exhibited high SUVmax." (PMID 34930376, 2021). "Glycolysis-related enzymes, such as ALDOA with nonenzymatic functions, positively regulate the HIF-1α/ALDOA feedback loops to increase the activation of MMP9 in lung cancer under hypoxia." (PMID 35008539, 2021). "In contrast, it was found on the other lung cancer cell line (H1339) that HSP90 activity inhibition with 17AAG or NVP-AUY922 conferred radiosensitization under both normoxic and hypoxic conditions via an HIF-1α-independent mechanism." (PMID 33806538, 2021). "Therefore, this study further explored miR-449a-mediated mechanism in lung cancer, mainly focusing on lysine demethylase 3A/hypoxia-induced factor-1α (KDM3A/HIF-1α) axis." (PMID 34044859, 2021). "Both lung cancer tissues and cells exhibited reduced miR-449a and raised KDM3A and HIF-1α levels." (PMID 34044859, 2021). "HIF-1α is upregulated under hypoxic conditions and stimulates the EMT of lung cancer cells." (PMID 34829545, 2021). "Previously, variations within the HIF1A gene have been associated with COPD, lung cancer and a host of non-pulmonary conditions." (PMID 34621299, 2021). "In lung cancer, ALDOA, one of the glycolysis- and gluconeogenesis-related enzymes, is activated by HIF-1α in a hypoxic environment and it promotes lactate increases, consequently prolonging the protein half-life of HIF-1α and forming a circuit regulation." (PMID 34572451, 2021). "We sought to investigate whether there are correlations between the expression levels of glycolytic genes HIF1A, GLUT1, HK2, and LDHA, in lung cancer patients and the rates of the patients’ survival." (PMID 34692483, 2021). "In lung cancer, miR-200c was shown to target both VEGF and HIF1A." (PMID 33673143, 2021). "In vitro, EGCG has been shown to inhibit growth by increasing the percentage of cells at the G0/G1 phase of the cell cycle and inhibit epithelial-mesenchymal transition and migration via downregulation of HIF-1α, VEGF, pAkt/ERK, COX-2 and vimentin in A549 lung cancer cell." (PMID 34650434, 2021).
lung carcinoma (continued). "In lung cancer (LC) cell lines, in which endogenous XPA levels are higher, inhibition of HIF-1α reduces the expression of XPA, while in LC cell lines with lower endogenous XPA, hypoxia elevates expression of HIF-1α and XPA." (PMID 32235701, 2020). "We determined that lung cancer patient tumor samples exhibit decreased miR-200b expression, and we further found this miRNA to inhibit tumor growth via interfering with ERK1/2 and AKT signaling, targeting p70S6K1 to suppress HIF-1α expression." (PMID 32435616, 2020). "Enriched KEGG pathways for different modules indicated that Jak‐Stat signalling, and PI3K‐Akt might contribute to lung carcinoma metastasis while VEGF signalling, NF‐κB signalling and HIF‐1α signalling were enriched in parental Lewis lung cells." (PMID 32750747, 2020). "We show that, in contrast to current beliefs, in lung cancer cells, the predominant and strong interaction with the Hif1α form of Fbp is not the liver (Fbp1) but in the muscle (Fbp2) isoform." (PMID 31947613, 2020). "While VEGFA was just parallel with HIF-1α in lung cancer tissues (r= 0.420, P<0.001), not in lung cancer cell lines (r=0.315, P=0.117)." (PMID 31892982, 2020). "Thus, we suspect that if the expression of CHCHD2 accompanies the HIF-1α expression participated in the regulation signaling pathways, so that lung cancer cells could adapt to hypoxic environment and play a role in angiogenesis, invasion, metastasis and metabolism of lung cancer." (PMID 32054470, 2020). "Furthermore, FOXO3 upregulates miR-622 to suppress hypoxia-inducible factor 1 alpha (HIF-1α) to induce cell invasion and migration in lung cancer." (PMID 32372224, 2020). "To determine whether the RASSF1A-HIF-1α signaling axis is operative in these cells, we carried out HIF-1α and RASSF1A knockdown, followed by 24 h hypoxic stimulation in these primary lung cancer cells." (PMID 31086178, 2019). "In addition, S. thunbergii-derived fucoidan inhibits angiogenesis by downregulating MMP-2 activity and VEGF/hypoxia-inducible factor-1α (HIF-1α) signaling in HUVEC cells and inhibits lung cancer cell A549 migration and proliferation." (PMID 31041568, 2019). "HIF-1α is higher expressed in patients affected by lung cancer with bone metastases than in patients without it." (PMID 31903166, 2019). "Additionally, HIF-1α expression has been significantly correlated with the expression of MYC and survivin in lung cancer." (PMID 29482638, 2018). "Furthermore, HIF1α can increase the phosphorylation of c-JUN, a downstream HIF1α molecule, and the expression of autophagy gene BECN1, which mediates radioresistance in lung cancer cells." (PMID 29688867, 2018). "In this study, we reported for the first time honokiol induced apoptosis, G1 arrest, as well as autophagy mediated cell death in KRAS mutant lung cancer cells, and honokiol blocked KRAS mutant lung cancer cells growth by activating mitochondrial Sirt3 and suppressing HIF-1α expression." (PMID 28443025, 2017). "The half-life of HIF-1α was significantly prolonged in the lung cancer cell line H1299 stably expressing wild-type HAUSP, but not in cells expressing HAUSP-CS, in the cycloheximide assay, which inhibits protein synthesis." (PMID 27934968, 2016). "We concluded that a block of EGF/ERK signaling may inhibit lung cancer metastasis via miR-622-mediated repression of the HIF-1α axis, which, as a consequence, precludes feedback inhibition of miR-622 level by HIF-1α." (PMID 26528854, 2015). "Importantly, ROS formation, ROS-dependent HIF1α stabilization and increased VEGF levels have been observed under normoxic conditions in hepatoma, lung carcinoma and osteosarcoma cell lines." (PMID 26584646, 2015). "In colon and lung cancer cells, KLF5 was shown to directly regulate the transcription of HIF1α." (PMID 25896712, 2015).
lung carcinoma (continued). "The control mice had significantly larger tumors and more extensive neovascularization, and the metastatic lung cancer tissues that lacked miR-622 overexpression had intensive staining for HIF-1α as assessed with immunohistochemistry." (PMID 26528854, 2015). "The importance of UCHL1 in the stabilization of HIF-1α and resultant activation of HIF-1 was also validated in clinical human tumours; the expression levels of UCHL1 correlated well with those of HIF-1α in both breast and lung cancers." (PMID 25615526, 2015). "However, there has been scant identification of potent tumor suppressor miRNAs that target HIF-1α to down-modulate EMT and thereby counteract the aggressiveness and metastasis of lung cancer cells." (PMID 26528854, 2015). "Our data demonstrate a role for miR-622 in repressing metastasis via inhibition of HIF-1α-related EMT signaling and thus suggest that miR-622 could be utilized as a promising target for the development of a lung cancer therapeutic." (PMID 26528854, 2015). "However, little work has been done to identify tumor suppressor microRNAs that target HIF-1α to down-modulate the EMT and thereby counteract the aggressiveness and metastasis of lung cancer cells." (PMID 26528854, 2015). "The role of HIF-1α in lung cancer has some controversy, and correlation between HIF-1α overexpression and adverse prognosis is not completely universal." (PMID 26316946, 2014). "We evaluated a three-protein signature consisting of a physiological protein (MUC1), a cancer-specific protein (HIF1A), and a lineage-specific protein (NKX2-1) that could discriminate lung cancer and its major subtypes with a low failure rate." (PMID 23028920, 2012). "HIF1A and NKX2-1 classified the major subtypes of lung cancer with a failure rate of 8.4%." (PMID 23028920, 2012). "In lung cancer, Giatromanolaki and coworkers found tumor HIF-2α-expression, not HIF-1α, to be independently associated with survival." (PMID 22454562, 2012). "In addition, we showed that SEMA3F protein correlated negatively with VEGF in lung cancer, and recently demonstrated that SEMA3F reduced VEGF mRNA level and HIF-1α protein level." (PMID 18781179, 2008). "Furthermore, our study reveals the critical role of HIF1A in mediating EMT and VM in lung cancer." (PMID 39912781, 2025). "Additionally, the negative feedback regulation between EZH2 and HIF‐1α is confirmed in lung cancer patient tissues and a database of cell lines." (PMID 38072662, 2024). "Moreover, PRMT5, desuccinylated by SIRT7, maintains the activation and stabilization of HIF-1α, which is essential to the phosphorylation of VEGFR2 as well as downstream Akt and endothelial nitric oxide synthase (eNOS) in lung cancer cells and ECs, playing a significant role in angiogenesis." (PMID 39519130, 2024). "Our study revealed the molecular mechanism of interrelation between HIF‐1α and EZH2 and provides a pharmacological basis for the dual targeting of HIF‐1α and EZH2, and the dual‐targeting compound DYB‐03 may be a promising candidate for the treatment of various cancer, such as lung cancer." (PMID 38072662, 2024). "Taken together, our findings indicate that abnormal expression of PRMT5 is closely related to the lung tumor stages and survival rates in patients with lung cancer, and PRMT5 may regulate angiogenesis, metastasis, and EMT through HIF-1α and PI3K/Akt signaling pathway." (PMID 37400960, 2023). "In another work, the flavonoids fisetin, luteolin, galangin, and quercetin were shown to inhibit hypoxia-induced VEGF formation in the lung cancer squamous cell carcinoma cell line NCI-H157, but concomitantly caused induction (rather than inhibition) of HIF-1α expression." (PMID 37830546, 2023). "In lung cancer, a study reported that HIF1A could mediate the immunosuppressive by the HIF1A/LOXL2/EMT pathways, and our results also showed that COPZ1 had a positive correlation with HIF1A, LOXL2 and EMT." (PMID 37107648, 2023).
lung carcinoma (continued). "In addition, hepatocyte growth factor (HGF), an inducer of HIF-1α, suppresses miR-519c maturation through an Akt-dependent pathway, indicating the important role of the HGF/miR-519c/HIF-1α axis in modulating angiogenesis in lung cancer." (PMID 35918758, 2022). "For instance, Hsu and colleagues demonstrated that lung cancer cells secrete an exosomal microRNA called mir23-a, which binds to the 3 ‘UTR region of PHD2, thus inhibiting its expression and promoting the transcriptional activity of HIF-1α, angiogenesis, and tumoral progression." (PMID 35565420, 2022). "However, we did not identify HIF-1α in this study; the molecular basis linking O-GlcNAcylated protein-mediated modulation of cancer metabolism and lung cancer cell invasiveness requires further investigation." (PMID 35008409, 2022). "Since we found that AK4 has a similar function both in non-malignant cells (PASMCs) and lung cancer cells, we can speculate that this might be one possible mechanism underlying the AK4-mediated HIF-1α increase observed in human PASMCs." (PMID 34638712, 2021). "Interestingly, lung cancer cells and their microenvironment were investigated at the level of the cellular metabolisms such as lactate or pyruvate dehydrogenases (LDH and PDK, respectively), glucose transporters (GLUT), and HIF-1α/2α." (PMID 34298636, 2021). "Based on the findings of the present study and previous knowledge about LINK-A and HIF1α hyper-activation, a similar function was supposed for LINK-A in lung cancer and the RNA expression change of some imperative genes which could be influenced by the silencing of LINK-A was examined." (PMID 33602983, 2021). "On the other hand, analysis of the same datasets did not support a relation of the BTG3/HIF1A ratios with patient survival in prostate and lung cancers, but showed a marginal effect in pancreatic cancer, consistent with our result that BTG3 did not have an obvious impact on HIF1A RNA expression." (PMID 33311481, 2020). "Moreover, our study demonstrates that in lung cancer cells, the predominant form of Fbp is Fbp2, not Fbp1, and that Hif1α interacts with Fbp2 much more strongly than with Fbp1." (PMID 31947613, 2020). "In hypoxia, HIF-1α promotes cell migration and invasion by inducing multiple genes, including the stromal cell-derived factor-1/C-X-C motif chemokine receptor-4 (SDF-1/CXCR-4) axis, C-C motif chemokine receptor 7 (CCR7), and lysyl oxidase (LOX) in lung cancer cells." (PMID 31061665, 2019). "In nearly 50% of the stage III lung cancer patients a marked increase in RASSF1A expression was noted, which may suggest that RASSF1Ahigh lung cancers are particularly aggressive and/or have a worse prognosis via regulation of HIF-1α and metabolic switch." (PMID 31086178, 2019). "Even if these miRNAs are upregulated in lung cancer tissue, it might be possible, that they are regulating other genes apart from HIF1A, which are not yet validated target genes and therefore not listed in the miRTarBase and not part of the prediction model." (PMID 27588394, 2016). "Furthermore, sequencing of the HIF-1α cDNA of H1339 lung cancer cells revealed no changes to the published HIF-1α coding sequence (NCBI Reference Sequence: NM_001530.3)." (PMID 22347438, 2012). "In addition, in lung cancer cells, inhibition of either EZH2 or HIF-1α could enhance the other’s function, which suggests that the prognosis for tumors might be enhanced by simultaneously inhibiting EZH2 and HIF-1α." (PMID 38911968, 2024). "However, whether SIRT3 can affect oxidative stress and HIF-1α expression in lung cancer cells by mediating ROS under hypoxic conditions has not been reported." (PMID 37747648, 2023). "For example, HIF-1α could promote ferroptosis by regulating SLC7A11 in hepatic stellate cell or HMOX1 in Leydig and Sertoli cell of testes, and it also was reported to inhibit ferroptosis by activating the Hippo‐YAP signaling pathway in non‐small cell lung cancer or lncRNA-PMAN in gastric cancer." (PMID 37415103, 2023).
lung carcinoma (continued). "Besides, the changes in caspase-3 activity also indicated that overexpression of WDR72 could not promote lung cancer stem cell apoptosis after inhibiting the AKT/HIF-1α pathway by LY29004." (PMID 36385964, 2022). "Finally, in A549 lung cancer cells it was shown that long-term (2 days) hypoxic incubation can increase the relative expression of PRKACA, indicating that this may occur independently of HIF-1α transcriptional regulation." (PMID 32111982, 2020). "Therefore we hypothesized that lung cancer cells with AK4-high/AK1-low represent a status of restricted energy demand as pathway and upstream regulator analyses revealed glycolysis and HIF-1α were the predominant metabolic pathway/transcription factor of the gene signatures." (PMID 31444368, 2019). "Collectively, we report a hitherto unrecognized crucial role of RASSF1A in regulating HIF-1α to promote hypoxia-driven gene regulation, metabolic switch and hyperproliferation in pulmonary hypertension as a non-malignant hypoxia-induced prototype disease and lung cancer." (PMID 31086178, 2019). "The Kd of the EGCG binding to HIF-1α is 3.47 μM, which is compatible to the highest plasma peak EGCG level (i.e. 7-10 μM) in the experimental animals administered with diet containing high dose of EGCG, suggesting the possibility that miR-210 may play a role inhibiting lung cancer in vivo." (PMID 25559244, 2014). "Quantitative gene expression patterns of CXCL12, CK7, CDH1, CTNNB1, HIF1A, MUC16, TGFBR2 and CD44v6 were analyzed from CTC, exosomes and cell free RNA of lung cancer patients with and without liver metastasis." (PMID 38877052, 2024). "Though we have confirmed the effects of miR-449a and KDM3A on lung cancer, and identified the targeting relation between miR-449a and KDM3A, as well as between KDM3A and HIF-1α, the internal mechanism of miR-449a/KDM3A/HIF-1α axis is not yet clear." (PMID 34044859, 2021). "Twenty-four hours after HCQ administration to CIS-treated lung cancer cells, we observed induction of HIF-2α, but not HIF-1α gene expression." (PMID 35127467, 2021). "In the case of lung cancer, the team determined that HIF-2α is the major factor that induces Wnt signaling, rather than HIF-1α." (PMID 31817513, 2019). "It has been reported that patients with lung cancer and positive HIF-1α expression in tumor tissues had lower overall survival rate than patients with negative HIF-1α expression." (PMID 29983647, 2018). "First, we studied the behavior of HIF‐1α, GLUT1, and CAIX in the lung cancer cell‐line A549 under normoxia and hypoxia." (PMID 28028936, 2017). "However, regardless of MIF overexpression and HIF-1α activation, the glucose metabolism index levels of AT2 cells after treatment were still significantly lower than those of H1703 and Calu-3 lung cancer cell lines." (PMID 41210694, 2025). "Furthermore, we found a negative correlation between the HIF‐1α and EZH2 dependency scores in lung cancer cell lines (Spearman cor =−0.24, p = 0.009), suggesting that lung cancer cells selectively rely on HIF‐1α or EZH2 for survival." (PMID 38072662, 2024). "Finally, to confirm the involvement of hypoxia in cancer development, we analyzed the level of HIF-1α inside EVs from COPD volunteers, who subsequently developed or not lung cancer." (PMID 37838700, 2023). "For instance, MOF overexpression promoted the cell proliferation, migration, and drug resistance of lung non–small cell lung cancer cells, whereas the lack of MOF resulted in the hypoxia tolerance and multidrug resistance of HCC cells through upregulated hypoxia-inducible factor-1α (HIF-1α)." (PMID 36212422, 2022). "Thus, we first sought to evaluate whether stabilization of HIF-1α under normoxic conditions sufficed to account for Rab5-GTP loading, by transfecting A549 lung carcinoma cells with wild type HIF-1α (HIF-1αWT), or a stable, non-hydroxylatable mutant of HIF-1α (HIF-1αP564A/P402A)." (PMID 33339852, 2020).